UBL5 (ubiquitin like 5)
Description:
Ubiquitin-like protein that plays a role in cell proliferation and sister chromatid cohesion by associating with spliceosomal proteins. Participates thereby in pre-mRNA splicing by maintaining spliceosome integrity. Promotes the functional integrity of the Fanconi anemia DNA repair pathway by interacting with FANCI component and subsequently mediating the formation of FANCI homodimers. Also plays a protective role against ER stress-induced apoptosis.
Synonyms: HUB1
Tractability: Small molecule: a structure with a bound ligand is known. PROTAC: ubiquitination databases record sites on it; its protein half-life has been measured.
Gene: Protein-coding gene on chromosome 19 (9,827,892 to 9,830,137, forward strand). Ensembl gene ENSG00000198258.
Subcellular location: Cytoplasm; Nucleus; Nucleus, Cajal body
Pathways (Reactome):
Metabolism of RNA: mRNA Splicing - Major Pathway
Gene Ontology:
Molecular function: protein binding; protein tag activity
Biological process: positive regulation of establishment of protein localization to mitochondrion; mRNA splicing, via spliceosome
Cellular component: cytoplasm; nucleus; nucleoplasm; Cajal body
Genetic constraint (gnomAD): Loss-of-function variants: 13 observed, 12.27 expected, observed/expected ratio (o/e) 1.06, 90% interval 0.69 to 1.66. The upper end of that interval is the gene's LOEUF score, 1.66, which puts it in group 6 of 6, group 1 being the genes least tolerant of losing a copy. Missense variants: 58 observed, 97.31 expected, observed/expected ratio (o/e) 0.6, 90% interval 0.48 to 0.74. Synonymous variants: 28 observed, 37.47 expected, observed/expected ratio (o/e) 0.75, 90% interval 0.55 to 1.02.
Homologues: Orthologues: chimpanzee UBL5 (100% identical), dog UBL5 (100% identical), macaque UBL5 (100% identical), guinea pig UBL5 (99% identical), mouse Ubl5 (99% identical), rabbit UBL5 (99% identical), tropical clawed frog ubl5 (93% identical), Drosophila melanogaster ubl (86% identical), Caenorhabditis elegans ubl-5 (81% identical).
Diseases named in the same sentence as UBL5 in open-access papers:
UBL5 is named in the same sentence as 13 diseases in open-access papers, as found by Europe PMC text mining. Sharing a sentence is not in itself a finding about the gene and the disease. The quoted sentences say what the papers report.
viral infection (3 papers, 2020 to 2024). "Evidence of the role of UBL5 in stress response, obesity, cancer, and viral infection is continuously growing." (PMID 39772229, 2024). "Simultaneously, UBL5 has been identified as a viral infection-related protein using comprehensive proteomic analyses." (PMID 39772229, 2024). "Here, we review recent progress in understanding the functions of UBL5 and discuss its putative role in viral infections." (PMID 39772229, 2024). "Nevertheless, studies on the precise function of UBL5 during viral infection remain rudimentary." (PMID 39772229, 2024). "Therefore, in this review, we summarize the recent progress in understanding the functions of UBL5 and discuss its putative role in viral infections." (PMID 39772229, 2024). "Therefore, UBL5 is an important link between viral infections and immunity, and its study will be beneficial for the prevention and treatment of viral infections in the future." (PMID 39772229, 2024). "This may be a promising avenue for future investigation in the study of viral infection and help to clarify the precise role of UBL5 in viral infections." (PMID 39772229, 2024). "This indicates that UBL5 may be important for the interaction between viral proteins and components of the spliceosome and viral infection." (PMID 39772229, 2024). "In addition to direct research on UBL5 and the virus, there is much evidence suggesting that UBL5 plays an important role in viral infection." (PMID 39772229, 2024). "Thus, more effective approaches are needed to determine the function of UBL5 in viral infections." (PMID 39772229, 2024). "This indicates that UBL5 may act as a key factor in the regulation of viral infections." (PMID 39772229, 2024). "However, UBL5 is likely to be an important host factor for viral infection." (PMID 39772229, 2024). "As research progresses, the functions of UBL5 are continuously being explored, such as in pre-mRNA splicing, DNA repair, and the UFP response, some of which have been reported to be important in viral infection." (PMID 39772229, 2024). "We here found that the 26S proteasome also degraded the p3 suppressor of RNA silencing of rice stripe virus to inhibit viral infection, and that the degradation was mediated by ubiquitin-like protein 5 (UBL5) but not by ubiquitin." (PMID 32866188, 2020). "UBL5 (ubiquitin-like protein 5), SNIP1 (Smad Nuclear Interacting Protein 1), TWISTNB (RNA Polymerase I Subunit F) and MFAP1 (Microfibril Associated Protein 1) have not been reported in affecting viral infection before." (PMID 39715740, 2024). "In addition, UBL5 can inhibit viral infection by binding to the non-structural protein 3 of rice stripe virus and mediating its degradation." (PMID 39772229, 2024). "However, a review of the current findings on the role of UBL5 in viral infection has not been undertaken." (PMID 39772229, 2024). "Notably, none of these studies have illustrated a positive role of UBL5 in viral infections." (PMID 39772229, 2024).
diabetes (2 papers, 2015 to 2021). "The UBL5 is a candidate gene for meat quality and IMF in the pig and also associated with body fat and fat accumulation related to metabolic dysfunction and diabetes in humans." (PMID 26042666, 2015).
Fanconi anemia (2 papers, 2021 to 2023). Fanconi anemia (FA) is a hereditary DNA repair disorder characterized by progressive pancytopenia with bone marrow failure, variable congenital malformations and predisposition to develop hematological or solid tumors. "UBL5 was also reported to be present in the Fanconi anemia complementation group I to maintain the functional integrity of the Fanconi anemia DNA repair pathway in mammalian cells." (PMID 37315790, 2023). "Several interactors of UBL5/Hub1 identified to date have suggested broad stress-responsive functions of the protein, for example, stress-induced control of pre-mRNA splicing, Fanconi anemia pathway of DNA damage repair, and mitochondrial unfolded protein response." (PMID 34502293, 2021).
melanoma (2 papers, 2020 to 2025). A malignant, usually aggressive tumor composed of atypical, neoplastic melanocytes. "After screening, we identified 3 genes, 26S proteasome non-ATPase regulatory subunit 14 (PSMD14), Ubiquitin-like protein 5 (UBL5), and BRCA1 Associated Protein 1 (BAP1), as DUBs related to melanoma growth." (PMID 33154524, 2020).
Alzheimer disease (1 paper, 2024). A progressive, neurodegenerative disease characterized by loss of function and death of nerve cells in several areas of the brain leading to loss of cognitive function such as memory and language. "Our study reveals common molecular pathways in Alzheimer's disease (AD) and atherosclerosis (AS), notably in genes like BEX2, NKRF, SOD1, UBL5, ZBTB17, and ZNHIT3." (PMID 38738952, 2024).
cancer (1 paper, 2023). A tumor composed of atypical neoplastic, often pleomorphic cells that invade other tissues. "Consistent with this, UBL5 deficiency induced catastrophic apoptosis in culture and inhibited tumorigenicity of cancer cells in vivo." (PMID 37315790, 2023). "Although UBL5 KD has been shown to induce apoptosis in cancer cell lines, little is known about the underlying mechanisms and physiological relevance." (PMID 37315790, 2023). "In agreement with this, UBL5 knockdown induced severe apoptosis in culture and suppressed tumorigenicity of cancer cells in vivo." (PMID 37315790, 2023).
infection (1 paper, 2021). The state of being infected such as from the introduction of a foreign agent such as serum, vaccine, antigenic substance or organism. "The ubiquitin-like protein 5 (UBL5) of rice and N. benthamiana interacts with p3 and mediates its degradation by the 26S proteasome, participating in plant defense against infection." (PMID 34066457, 2021).
tumor (1 paper, 2023). "Furthermore, the stable UBL5 KD cells became poorly tumorigenic after implantation to immunodeficient NOD scid gamma mice compared with the Ctrl-shRNA-transduced cells, indicating that proper expression of UBL5 is required for the survival of these tumor cells in vivo." (PMID 37315790, 2023).
UBL5 also shares sentences with these, for which no sentence is quoted: Obesity (2 papers); atherosclerosis (1); metabolic disorders (1); neuroblastoma (1); Parkinson disease (1).